OGN (osteoglycin)
Diseases named in the same sentence as OGN in open-access papers (continued):
Sharing a sentence is not in itself a finding about the gene and the disease.
tumor (35 papers, 2011 to 2025). "Aberrant OGN activation is associated with high tumour invasiveness and poor prognosis in OC patients." (PMID 35227296, 2022). "OGN expression in DF is highest compared with SF in 26 upregulated proteins, previous studies have shown loss of OGN expression in cancer cell lines and different tumors, suggesting its potential role as a tumor-suppressor gene." (PMID 31673248, 2019). "The new data also revealed a higher enrichment of mast cells in tumor tissues, and nearly all fibroblast subtypes were identified, except for OGN + CAF." (PMID 39354287, 2025). "Based on a quantitative comparison between tumor and NAT ECM, we observed a substantial loss of PROs (i.e., DCN, OGN, LUM, and HAPLN1)." (PMID 40032993, 2025). "miR-1290 overexpression in CAFs increased miR-1290 expression and inhibited OGN expression in tumor tissues and OGN overexpression in CAFs increased OGN expression." (PMID 38402185, 2024). "In this study, cancer-associated fibroblasts (CAFs) and normal fibroblasts (NFs) were isolated from tumor-containing and normal omenta, respectively, and the downregulation of osteoglycin (OGN) in CAFs was observed." (PMID 38402185, 2024). "According to GSE14407, OGN was shown to be remarkably downregulated within the tumor epithelium than in a normal ovarian surface epithelium." (PMID 38402185, 2024). "According to GSE40595, OGN was shown to be dramatically downregulated within the tumor epithelium than in a normal ovarian surface epithelium." (PMID 38402185, 2024). "OGN serves as an anti-tumor factor inhibiting the capacity of tumor cells to proliferate, invade, and/or migrate in other cancers." (PMID 38402185, 2024). "In nude mouse xenograft tumor models, OGN overexpression in CAFs suppressed tumor growth, whereas miR-1290 overexpression in CAFs increased tumor growth." (PMID 38402185, 2024). "OMD (osteomodulin) is involved in osteoblast differentiation and OGN (osteoglycin) regulates bone and glucose homeostasis and has been indicated as a tumor suppressor." (PMID 36980828, 2023). "OGN is involved in the formation and regulation of ECM, and low expression of OGN is involved in the regulation of tumor lymphatic metastasis, promotion of angiogenesis, and promotion of invasion and metastasis of tumor cells." (PMID 37251946, 2023). "The qRT-PCR results of subcutaneous tumour tissues showed that the expression of miR-5003-3p was downregulated after the overexpression of circ_0087429, while the expression of OGN was upregulated." (PMID 35513835, 2022). "According to a bioinformatic analysis, OGN plays vital roles in immune surveillance and tumor progression in papillary thyroid cancer." (PMID 36421687, 2022). "Based on existing data and in a cancer-type-specific manner, OGN has been characterized as both an anticancer chemical and a tumor promoter, which depends on the tumor type." (PMID 36421687, 2022). "OGN controls tumor cell proliferation by a variety of methods, either increasing or inhibiting cancer growth, according to numerous studies." (PMID 36421687, 2022). "The western blotting and immunohistochemical staining results showed that the expression of OGN and E-cadherin was increased, and the expression of N-cadherin was decreased in tumour tissues overexpressing circ_0087429." (PMID 35513835, 2022). "The connection of PDIA4 and OGN with tumor progression is relatively recent, PDIA4 has been found overexpressed in a cohort of EOC patients, and associated with poor prognosis, cell gowth and resistance." (PMID 35197484, 2022).
tumor (continued). "CDH3 was highly expressed in tumor samples, whereas high expression of CTGF, CYR61, OGN, FGF13, and CHRDL1 was associated with better prognosis and appeared to be a protective factor." (PMID 33816258, 2021). "Decreased OGN expression has been described in several malignancies, and for this reason, even if its precise role remains undefined, it is thought to be a tumor suppressor." (PMID 32545553, 2020). "COL3A1, COL1A2, COL15A1, ASPN, and MXRA5 were higher expressed in tumor samples, while OGN was lower expressed." (PMID 32300359, 2020). "Collectively, our work identifies decreased OGN expression in CRC impaired EGFR internalization as a novel mechanism through which tumor cells induce EGFR activity to sustain proliferative signaling." (PMID 29499765, 2018). "OGN over-expression in cancer cells led to a decrease in growth rate and final mean tumor volume compared with control cells." (PMID 29499765, 2018). "Functional assessment of OGN overexpression in vitro revealed a higher proliferation rate than control cells at 72 h as well as more active tumor cell colony formation in soft agar." (PMID 28923059, 2017). "In contrast, a number of genes described as tumor suppressors (among them osteoglycin, dermatopontin and secreted frizzled-related protein 4) were significantly upregulated after combination therapy." (PMID 25127546, 2014). "This anti-ECM cleaving property contributed to OGN's tumour suppressor role in hepatocarcinoma cells by attenuating tumour cell migration." (PMID 22084683, 2011). "Many cancer cell lines lack the expression of OGN, suggesting that it may serve as a tumor suppressor gene in the development of cancer." (PMID 40051609, 2025). "Furthermore, OGN’s tumor suppressor activity in BC is demonstrated to be mediated by its effect on the PI3K/AKT/mTOR pathways." (PMID 40051609, 2025). "Finally, in nude mouse xenograft tumor models, OGN overexpression in CAFs suppressed tumor growth, whereas miR-1290 overexpression in CAFs increased tumor growth." (PMID 38402185, 2024). "Being a matrix molecule, OGN might play a role in the ability of tumor cells to adhere, thereby affecting their capacity to migrate and invade, as exemplified by our study." (PMID 38402185, 2024). "It suggests that OGN may participate in the regulation of tumor immunity to inhibit the progress of cancer, thus affecting the prognosis of patients." (PMID 37352032, 2023). "OGN may affect the epithelial mesenchymal transformation (EMT) of tumor by affecting the infiltration of tumor immune cells." (PMID 37352032, 2023). "The tumorigenic process is connected to OGN, which could be employed as a biomarker for tumor prognosis." (PMID 36421687, 2022). "It is reported that the expression of OGN is reduced in many different tumours." (PMID 35513835, 2022). "Moreover, tumor-suppressor activity was observed in mouse melanoma cell lines as overexpression of OGN increased stress-triggered cell death autophagy following ER induction through LIP-mediated pathways following ER stress." (PMID 36421687, 2022). "It highlights the importance of OGN-mediated EGFR signaling in inhibiting tumor development." (PMID 36421687, 2022). "Interestingly, we found POSTN and OGN were common in all classification, indicating their key role in the tumor microenvironment and tumor progression." (PMID 33530209, 2021). "Interestingly, CDH3 (r=-0.101, p=2.59E-02) and OGN (r=-0.104, p=2.09E-02) was negatively correlated with tumor purity." (PMID 33816258, 2021). "This subexpression was also verified at the protein level by immunohistochemistry: Healthy tissue displayed a moderate expression of OGN in the stroma, whilst in tumoral tissues only weak staining was detected in the tumor cells and very little in the stroma (p < 0.001, Wilcoxon test)." (PMID 34440771, 2021). "POSTN and OGN are crucial in modulating the microenvironment and tumor biology for HNSCC." (PMID 33530209, 2021).
tumor (continued). "These collective results indicate the tumor repressor role of OGN in BCa cells." (PMID 32922434, 2020). "Similarly to decorin, osteoglycin was expressed in normal connective tissue and decreased in the tumor stroma." (PMID 24634138, 2014). "OGN may exert its function of affecting EMT by affecting the infiltration of tumor immune cells." (PMID 37352032, 2023). "It is reported that miR-5003-3p and OGN may participate in the EMT of tumours." (PMID 35513835, 2022). "Also, CDH3 and OGN expression were positively correlated with tumor purity." (PMID 33816258, 2021). "We found that CAF subtypes 0 (BTG1+ CAF), 2 (CFD+ CAF), and 4 (IGFBP7+ CAF) were more abundant in the tumor than the normal, while CAF subcluster 1 (OGN+ CAF), 3 (C1R+ CAF), 5 (MFAP5+ CAF), and 6 (SFRP4+ CAF) were more abundant in the normal than the tumor." (PMID 38686196, 2024). "In the bulk sequencing data, we stratified the tumor samples into two groups according to the median expression of the marker genes (SFRP4, CLU, OGN)." (PMID 38686196, 2024). "This is coherent with the results of our dataset analysis, in which we found they showed a strong correlation with the tumor phenotype, with TOP1 and PDIA4 positively correlating and OGN being negatively correlated." (PMID 35197484, 2022). "Under-expressed OGN and EFS, compared to the normal samples, improved survival, reduced tumor recurrence, and reversed the epithelial to mesenchymal transition by inhibiting EGFR/AKT/Zeb-1 in tumors." (PMID 35741697, 2022). "CDH3 was found to be highly expressed, while CTGF, CYR61, CHRDL1, OGN and FGF13 had significantly lower expression in tumor tissues compared with peri-tumor tissues." (PMID 33816258, 2021). "Comparing with peri-tumor controls, the expression of CTGF, CYR61, CHRDL1, OGN and FGF13 were significantly decreased, whereas CDH3 significantly increased in PTC tissues which were consistent with the bioinformatics results obtained by TCGA dataset." (PMID 33816258, 2021). "Proteomic analysis reveals proteins associated with the formation of atherosclerosis, including mimecan (osteoglycin), Ras-1 suppressor protein (RSUP-1) and cathepsin D, which are simultaneously identified as biomarkers of cancer tumours." (PMID 34948066, 2021). "Above all, our experimental approach has yielded novel findings that OGN can affect EMT, a vital mechanism involved in tumor development and progression." (PMID 29499765, 2018). "Therefore, our study found that during PCa pathogenesis, the disorganized expression of CRISP3, OGN, SPOCK3, COL4A6, CCBE1, and FLRT3 leads to ECM dysfunction and promotes angiogenesis and tumor development." (PMID 37251946, 2023). "The expression of OGN was absent in several cancer cell lines, implicating its potential role as a tumor suppressor gene in cancer biology, although its physiological function has not been fully elucidated." (PMID 24587265, 2014). "Furthermore, OGN is expressed in various cancer tissues and has been reported to have a positive or negative correlation with tumor progression." (PMID 36421687, 2022). "OGN underexpression, specifically, was related to better outcomes in terms of event free survival, relapse or progression, indicating its possible utility as a marker of disease aggressiveness regardless of the stage of the tumor at diagnosis." (PMID 34440771, 2021). "Thus, our findings highlight the importance of the OGN-mediated of EGFR signaling in tumor biology, revealing a novel mechanism regulating CRC growth and progression." (PMID 29499765, 2018).
cancer (30 papers, 2014 to 2025). A tumor composed of atypical neoplastic, often pleomorphic cells that invade other tissues. "According to our results, higher levels of SYNM and CNNN1 were found to be positively associated with increased IC50 values of cancer therapy drugs, whereas the expression of OGN and C2orf40 exhibited an opposite correlation." (PMID 37605453, 2023). "In addition to these functions, OGN is found in a variety of cancer tissues and is implicated in cellular processes linked to tumorigenesis, including cell proliferation, invasion, metastasis, and epithelial-mesenchymal transition (EMT)." (PMID 36421687, 2022). "Hence, Kaplan-Meier analysis showed the OGN expression was markedly associated with longer time post-surgical resection, with prolonged cancer specific survival as 75.7 months in the High OGN expression group versus 61.6 months in the Low OGN expression group." (PMID 29499765, 2018). "According to GSE38666, OGN was shown to be dramatically downregulated within cancer stroma than that in normal stroma." (PMID 38402185, 2024). "SFRP4 and OGN have been identified as the core genes of EC and cancer cell-derived exosome progression, which are closely related to the occurrence and progression of EC." (PMID 37352032, 2023). "The CIBAR1, CLIC4, OGN, and ZNF483 are protein-coding genes, but nothing is known about their association with PCa and cancer in general." (PMID 37298233, 2023). "GSEA enrichment analysis showed that OGN was mainly enriched in cancer-related signaling pathways such as EMT and KRAS." (PMID 37352032, 2023). "Here, LCP1, PRDX2, OGN and, TAGLN2 together with other molecular interactors, linked with highest hits, according to KEGG database, to pathways in cancer, PI3K-AKT and MAPK signaling pathways." (PMID 38322285, 2023). "In this cancer type, the correlation between OGN expression and T-cell densities was verified by immunohistochemistry." (PMID 36421687, 2022). "Similar to other SLRPs, OGN is involved in signal transduction that mediates a variety of responses in relation to cancer progression." (PMID 36421687, 2022). "This review aims to improve our understanding of OGN and provide some new strategies for the treatment of fibrosis and cancer." (PMID 36421687, 2022). "Several studies examining the role of OGN in tumorigenesis have concluded that OGN plays an important role in forming the cancer microenvironment." (PMID 36421687, 2022). "A small fraction of cells aggregated into OGN+ fibroblast populations, indicating that OGN+ fibroblast populations dramatically decreased in cancer tissues." (PMID 36463319, 2022). "The current review will concentrate on the role of OGN in controlling the fibrosis and tumorigenesis processes, including a number of pathologies related to fibrosis and cancer." (PMID 36421687, 2022). "Numerous studies have validated the expression pattern of OGN in various types of malignancies, and the expression level of OGN has been observed to vary in different forms of cancer." (PMID 36421687, 2022). "In rescue experiments, cancer cells with stable ectopic OGN expression were transiently transfected with Zeb-1, Slug or Snail." (PMID 29499765, 2018). "Consistently, multivariate analysis after adjustment revealed that OGN expression was also independent prognostic factor for cancer specific survival in CRC patients, besides T stages and adjuvant therapy (P < 0.05)." (PMID 29499765, 2018). "Despite numerous studies demonstrating altered OGN expression in cancers, functional data on how OGN involved in cancer pathology are lacking, and further research is needed." (PMID 29499765, 2018). "Here we aim to evaluate the relationship between OGN expression patterns and the clinical course of CRC, and the role of OGN in cancer progression." (PMID 29499765, 2018).
cancer (continued). "Decreased OGN expression was observed in a variety of different cancers including gastric cancer, colorectal adenoma, squamous cervical and vaginal cancer, invasive ductal breast carcinoma, laryngeal carcinoma, in comparison with control normal tissues." (PMID 29499765, 2018). "In most cases, PFN1, NCL and CNDP2 exerted an increased mRNA expression, while OGN displayed a decreased level in the carcinoma tissues compared with the adjacent normal tissue." (PMID 24587265, 2014). "Additionally, the RNA gene Y_RNA was found to be upregulated in 10 cancer types and C7 and OGN genes were downregulated in 15 cancers." (PMID 38763334, 2024). "In the paired samples, the down-regulation of OGN expression in cancer tissues was also found." (PMID 37352032, 2023). "On the other hand, a decrease in OGN expression was found in different types of cancers." (PMID 35197484, 2022). "As a result, OGN could be a potential cancer biomarker, but its characterization in various cancers is still unknown." (PMID 36421687, 2022). "Our findings of OGN-dependent regulation of EGFR internalization add alternative mechanism to a growing body of evidence that highlights the importance of receptor endocytosis in cancer progression." (PMID 29499765, 2018). "So, it was not a surprise that OGN expression was markedly associated with longer survival time, with prolonged cancer specific survival as 75.7 months in the High OGN expression group versus 61.6 months in the Low OGN expression group." (PMID 29499765, 2018). "Understanding the effect of OGN in tumorigenicity requires consideration of the cancer cell per se and the microenvironment established by complex interactions between the host and the cancer cell." (PMID 29499765, 2018). "However, the majority of studies on OGN in cancer indicate its antitumorigenic function." (PMID 36421687, 2022). "However, the OGN+ matrix-producing fibroblasts were dramatically decreased in cancer tissues." (PMID 36463319, 2022). "Other marker genes of SFRP4+ CAFs, such as OGN and CLU, also influenced cell proliferation and invasion and cancer initiation, respectively." (PMID 38686196, 2024). "Herein, we showed that esophageal cancer-related gene-4 (ECRG4), which is downregulated in BCa tissues and cell lines, has a positive correlation with osteoglycin (OGN)." (PMID 32922434, 2020). "Most interestingly, we found that OGN is highly expressed in IPF, but is lowly expressed in cancer tissues." (PMID 32300359, 2020). "We found seven upregulated genes (MCM10, RAD51-associated protein 1 (RAD51AP1), KIF2C, Y_RNA, FAM64A, CDC6, and CDCA8) and six downregulated genes (ADAMTS8, ATP1A2, MYH1, OGN, OMD, and ZBTB16) in at least two phenotypes containing either ALT high/middle or TEL high/middle regardless the cancer type." (PMID 38763334, 2024). "Reduced OGN (osteoglycin) expression has been found in various types of cancers compared with normal tissues, and higher OGN expression is an indicator of increased survival and reduced cancer recurrence." (PMID 33644115, 2021). "Thus, our results based on functional network analysis and thus a predictive bioinformatic model could indicate that PRDX2, LCP1, OGN and TAGLN2 might impact the IPF progression through mechanisms common to cancer." (PMID 38322285, 2023).
cardiac diseases (2 papers, 2017 to 2020). "Moreover, nothing is known about the glycosylation state of OGN during different forms of cardiac diseases and the impact of this glycosylation on cardiac inflammation or fibrosis." (PMID 27878326, 2017). "Together with another group of four proteins from the SLRP family, namely fibromodulin (FMOD), osteomodulin (OMD), osteoglycin (OGN) and lumican (LUM), the importance of extracellular remodeling processes in heart disease is emphasized." (PMID 32670412, 2020).
cardiovascular disease (2 papers, 2022 to 2023). "In 2008, OGN was first discovered to be related to the ventricular mass, which laid a foundation for further research on the role of OGN in cardiovascular disease." (PMID 36863704, 2023). "Evidence for the involvement of OGN in the fibrosis of cardiovascular disease is abundant." (PMID 36421687, 2022). "A meta-analysis revealed that the blood concentration of OGN in patients with cardiovascular disease is significantly elevated compared to that in control patients, indicating that OGN may play an important role in cardiovascular disease." (PMID 36421687, 2022).